PTBP1 (polypyrimidine tract binding protein 1)
Diseases named in the same sentence as PTBP1 in open-access papers (continued):
Sharing a sentence is not in itself a finding about the gene and the disease.
glioma (46 papers, 2011 to 2025). A benign or malignant brain and spinal cord tumor that arises from glial cells (astrocytes, oligodendrocytes, ependymal cells). "The results of these studies suggest that the main reason for PTBP1 as a prognostic risk factor is that PTBP1 can indicate glioma progression and IDH1 mutation status." (PMID 38918441, 2024). "Following EV-A71 infection in glioma cells, PTBP1, one of the downregulated DEGs, was found to be associated with multiple categories of GO and KEGG enrichment analysis." (PMID 37808305, 2023). "The objective of this study was to examine the association between PTBP1 and EV-A71 infection in glioma cells, as well as evaluate the role of PTBP1 in patients diagnosed with LGG and GBM." (PMID 37808305, 2023). "Our findings revealed that PTBP1 was highly expressed in glioma, especially in GBM, and associated with pathological grade and predicted poor prognosis of patients, representing a potential therapeutic target." (PMID 35299889, 2022). "High expression of PTBP1 was significantly associated with poor prognosis in glioma, and it was an independent risk factor in glioma patients." (PMID 35299889, 2022). "PTBP1 dysregulation has been linked to the onset and development of prostate and ovarian cancer, whereas PTBP1 overexpression is associated with the aggressiveness of glioma, colorectal and breast cancer." (PMID 35585060, 2022). "In the context of gliomas, PTBP1 expression correlates with WHO grade and IDH1 mutation status." (PMID 38918441, 2024). "Furthermore, high expression of PTBP1 has been demonstrated to be associated with the aggressive behavior of several types of cancer, especially in glioma and ovarian tumors." (PMID 35600383, 2022). "In glioma cells, PTBP1 stabilizes PFKFB4 mRNA to promote glycolysis, whereas in gastric cancer cells, it accelerates the degradation of TXNIP mRNA to alleviate oxidative stress.​​." (PMID 41313521, 2025). "For instance, PTBP1 lactylation was found to facilitate glioma stem cell maintenance through PFKFB4-driven glycolysis." (PMID 41035644, 2025). "In the database, 8.6% (95/1099) of glioma patients were found to carry PRGs gene variations, with PTBP1 accounting for the highest proportion at 2.8%." (PMID 41438761, 2025). "The results showed that as the malignancy of gliomas increased, more malignant cells expressing PTBP1 protein became available." (PMID 38918441, 2024). "The results demonstrate that increased PTBP1 is an important molecular marker of glioma progression." (PMID 38918441, 2024). "We have demonstrated using immunohistochemistry in gliomas of different grades that PTBP1 protein expression rises with glioma progression." (PMID 38918441, 2024). "To investigate the expression of PTBP1 in different cell types within gliomas, we compared its expression levels in four cell types, with AC-like Malignant (astrocytic differentiation) serving as the reference." (PMID 38918441, 2024). "Lastly, we investigate the involved upstream RNA-binding proteins (RBPs) and identify PTBP1 as a promising therapeutic target to dampen the malignant AS signature while promoting neuronal-like differentiation in glioma cells." (PMID 38662454, 2024). "To further demonstrate the prognostic impact of PTBP1, we validated the relationship between PTBP1 expression and glioma (LGG/GBM) prognosis in three separate datasets, CGGA mRNA_325,CGGA mRNA_301, and CGGA mRNA_693, respectively." (PMID 38918441, 2024). "Consistent results were obtained across three independent CGGA glioma cohorts, reinforcing PTBP1 expression as a potential molecular marker for assessing LGG progression and prognosis." (PMID 38918441, 2024). "In conclusion, the cellular localization studies of PTBP1 expression in gliomas revealed its widespread expression across different cell types, with AC-like Malignant cells showing significant differences compared to other cell types." (PMID 38918441, 2024).
glioma (continued). "We then assessed the therapeutic vulnerability of targeting PTBP1 in glioma by using an antisense oligonucleotide–based (ASO-based) therapy." (PMID 38662454, 2024). "Taken together, PTBP1 expression is influenced by IDH1 mutations and the degree of tumour malignancy, and is associated with poor prognosis in gliomas." (PMID 38918441, 2024). "Studies also indicated that PTBP1 was upregulated in glioma tissues, and promote the malignant phenotype of glioma cells 46, however, its regulatory network and potential treatments need further exploration." (PMID 39431006, 2024). "We propose that targeting the AS regulator PTBP1 and/or other key RBPs that regulate AS landscapes represents a potential avenue for neuronal-like differentiation therapy in glioma, particularly in GBMs." (PMID 38662454, 2024). "To demonstrate the relationship between glioma grade and PTBP1 expression in the TCGA LGG cohort, we compared the difference in PTBP1 expression between Grade2 and Grade3." (PMID 38918441, 2024). "Considering the involvement of PTBP1 in all categories of GO and KEGG enrichment analysis, we conducted an analysis using the publicly accessible TCGA database to examine the PTBP1 status in normal brain and glioma tissues." (PMID 37808305, 2023). "As a continuation of this research, we will assess the molecular mechanism of PTBP1 following EV-A71 infection in glioma." (PMID 37808305, 2023). "The significance of PTBP1 in EV-A71-infected glioma and its potential role in expression levels in glioma have been strongly suggested, highlighting the light spot of this study." (PMID 37808305, 2023). "The as-lncRNA PTB-AS has been found to significantly promote the occurrence of glioma by pairing with the extended base of the PTBP1 3′UTR with the assistance of SND1 to maintain the level of PTBP1." (PMID 37189431, 2023). "To assess its potential anti-tumor efficacy, we subsequently evaluated the impact of PTBP1 expression on immune infiltration in gliomas using the ssGESA algorithm." (PMID 37808305, 2023). "Immunohistochemical staining was utilized to measure the protein levels of PTBP1 in human glioma samples." (PMID 37808305, 2023). "Here, we clarified circYIPF6 expression in glioma and revealed the molecular mechanism by which circYIPF6 regulated PTBP1 level via sponge miRNA and thus regulated cell proliferation, apoptosis, and glycolysis of glioma cells." (PMID 37588107, 2023). "Overall survival (OS) or disease-free survival (DFS) was evaluated to analyze the relation between PTBP1 expression levels and prognosis of glioma patients." (PMID 37808305, 2023). "Consistent with previous findings, our study revealed a significant correlation between PTBP1 level and advanced tumor stage at both the mRNA and protein expression in glioma." (PMID 37808305, 2023). "We further analyzed the regulation of miR-760 on PTBP1 level and found that overexpression of miR-760 downregulated PTBP1 expression in glioma cells (P < 0.01)." (PMID 37588107, 2023). "Our research uncovered a critical role of PTBP1 in outcomes and immune cell infiltration of glioma patients, particularly in those with LGG." (PMID 37808305, 2023). "We observed elevated expression levels of PTBP1 across various tumor grades of glioma in comparison to normal brain samples." (PMID 37808305, 2023). "We observed that in the total cohort of glioma cases, lower levels of PTBP1 significantly correlates with 1p/19q co-deletion (p = 4.5e-11)." (PMID 37808305, 2023). "The analysis revealed a pronounced relative overexpression of PTBP1 in glioma tissues when compared to normal cerebral cortex tissues." (PMID 37808305, 2023). "Functional rescue expression results revealed that circYIPF6 performed its role in glioma through sponging miR-760 to regulating PTBP1 expression." (PMID 37588107, 2023).
glioma (continued). "Further, our studies revealed that PTBP1 promoted glioma progression by regulating alternative splicing of ITSN1, which further confirmed the important function of alternative splicing in cancer." (PMID 36171198, 2022). "PTBP1 expression was significantly higher in grade 4 than in either grades 2 (P < 0.001) or 3 (P < 0.001), and PTBP1 expression in grade 3 glioma was higher than that in grade 2 (P = 0.0038)." (PMID 35299889, 2022). "Subsequently, silencing PTBP1 inhibited glioma cell proliferation, migration, and invasion by down-regulating the ratio of ITSN1-S/ITSN1-L." (PMID 36171198, 2022). "PTBP1 was high expressed in glioma, and it significantly correlated with poor prognosis, suggesting a potential therapeutic target for glioma, particularly for GBM." (PMID 35299889, 2022). "In this study, we analyzed the expression, prognostic value, and potential mechanism of PTBP1 by immunohistochemistry in a single-center cohort of 150 glioma patients and by a comprehensive bioinformatics analysis of TCGA and CGGA databases." (PMID 35299889, 2022). "Together with previous studies, our work illustrated that splicing control of the ratio of ITSN1-S/ITSN1-L is an important aspect in glioma progression and suggested the usage of PTBP1 as a promising therapeutic target for gliomas." (PMID 36171198, 2022). "Taken together, we concluded that PTBP1 promoted glioma progression by regulating alternative splicing of ITSN1." (PMID 36171198, 2022). "LncRNA MIR155HG was highly expressed in glioma tissues and promoted glioma resistance to TMZ by binding PTBP1 to regulate the Wnt/β-catenin pathway." (PMID 35912271, 2022). "To further explore the potential upstream mechanism of PTBP1 involved in glioma progression, we predicted 126 transcription factors (TFs) related to PTBP1 through the GCBI database and screened out 74 TFs using the Funrich software." (PMID 35299889, 2022). "The results demonstrated that PTBP1 expression was an independent prognostic factor for OS in glioma (hazard ratio (HR), 4.901; 95% confidence interval (CI), 2.778-8.645; and P < 0.001)." (PMID 35299889, 2022). "In conclusion, these results demonstrate PTBP1 serve as a promising prognostic biomarker in glioma, and patients with high-PTBP1 expression need more aggressive treatment." (PMID 35299889, 2022). "Our aim was to investigate the expression, functional role, and prognostic value of PTBP1 in glioma." (PMID 35299889, 2022). "In summary, our present study demonstrated that the splicing factor PTBP1 promotes proliferation and mobility of glioma cells by controlling ITSN1 pre-mRNA splicing and up-regulating the expression ratio of ITSN1-S/ITSN1-L." (PMID 36171198, 2022). "There is increasing evidence that PTBP1 can involve in the alternative splicing of multiple genes in glioma and play a promoting role in glioblastoma tumorigenesis." (PMID 35299889, 2022). "Contrarily to our results about circ_0076611 expression, PTBP1 had been previously shown to induce the expression of another circRNA, circRNA_001160, in glioma endothelial cells." (PMID 35710947, 2022). "Meanwhile, the glioma patients with higher PTBP1, SLC39A1, MMP9, and SLC16A3 expression had shorter OS (p < 0.01)." (PMID 36307882, 2022). "For instance, PTBP1 can enhance glioma proliferation and migration by increasing the inclusion of exon 3 in RTN4 mRNA." (PMID 34733320, 2021). "We found that TFs encoded by HOX genes recurrently appeared in glioma, and these TFs regulated critical genes (such as MAML2, CDK6, FAM84B, and PTBP1)." (PMID 33537074, 2021).
glioma (continued). "PTBP1 is known to play oncogenic functions in some kinds of cancers, including gliomas, breast, bladder, pancreatic and colon cancers." (PMID 31291975, 2019). "PTBP1 and HNRNPs are recognized as important splicing factors in glioma progression that regulate various splicing events, which is also reflected in our analysis." (PMID 31729991, 2019). "The combined use of PTBP1, circRNA_001160 and miR-195-5p enhanced the role of Dox in promoting apoptosis in glioma cells." (PMID 31862871, 2019). "It is consistent that miR-124, miR-149 and miR-339-5p, three miRNAs that target PTBP1, a protein that was found in high amounts in gliomas, were down-regulated." (PMID 21655185, 2011). "We discovered that some targets of these microRNAs such as STAT3, PTBP1 or SIRT1 are differentially expressed in gliomas consistent with deregulation of microRNA expression." (PMID 21655185, 2011). "Consequently, highly expressed LINREP confers protection upon polypyrimidine tract-binding protein 1 (PTBP1) against degradation, thereby significantly impeding ASEs and promoting glioma progression." (PMID 40469294, 2025). "PTBP1 can be used as a marker of inflammation, progression and prognosis in gliomas." (PMID 38918441, 2024). "We also explored the spatial transcriptome of PTBP1 expression in gliomas." (PMID 38918441, 2024). "By focusing on low-grade gliomas, the study found that PTBP1 could be used as a molecular marker of LGG to indicate cancer progression, immune infiltration, and prognosis." (PMID 38918441, 2024). "We also investigated the potential of PTBP1 as an independent prognostic marker for glioma." (PMID 38918441, 2024). "Therefore, PTBP1 expression at the single-cell level serves as an indicator of the progression of glioma cancer cells." (PMID 38918441, 2024). "In glioma, PTBP1 bound to the pre-mRNA of ANKRD17 to promote circANKRD17 expression." (PMID 38993556, 2024). "In our study, we showed that higher PTBP1 expression indicated poorer prognosis in glioma patients." (PMID 39431006, 2024). "Next, we explored the impact of PTBP1 expression in low-grade gliomas." (PMID 38918441, 2024). "Characteristics of patients with glioma according to PTBP1 expression level." (PMID 37808305, 2023). "Here, we explored whether 1p/19q co-deletion (codel) status may correlate with PTBP1 gene expression in glioma." (PMID 37808305, 2023). "Functional rescue experiments showed that both miR-760 inhibition and PTBP1 overexpression could attenuate the regulatory effect of circYIPF6 silencing on glioma cells." (PMID 37588107, 2023). "In summary, this study revealed a novel molecular pathway that regulated glioma progression, suggesting that the circYIPF6/miR-760/PTBP1 axis might be a potential therapeutic target for glioma." (PMID 37588107, 2023). "Overexpression of PTBP1 increased the level of PTBP1 in glioma cells (P < 0.001)." (PMID 37588107, 2023). "In glioma, PTBP1 was found upregulated and involved in the tumorigenesis of glioma." (PMID 37588107, 2023). "Moreover, a stronger intensity and more quantity of PTBP1 protein staining were found in high-grade glioma, compared with low-grade glioma." (PMID 37808305, 2023). "Moreover, an RNA analysis conducted on Chinese human glioma tissues indicated a progressive increase in PTBP1 expression from WHO II to WHO IV stages, providing further confirmation of the distinctive PTBP1 status within glioma (p < 0.001)." (PMID 37808305, 2023). "Moreover, the PTBP1 and hnRNPA1 expression in glioma and neuroblastoma is regulated by MYC, a protein which is often overexpressed in cancer and can impair alternative splicing." (PMID 36230624, 2022). "Kaplan-Meier method was used to evaluate the prognostic effect of PTBP1 in glioma." (PMID 35299889, 2022). "Several pieces of evidence support the role of PTBP1 in the development and progression of gliomas." (PMID 35299889, 2022).
glioma (continued). "Importantly, we found PTBP1 was closely related to prognosis in glioma, with high expression indicating poor prognosis both in our study and CGGA and TCGA datasets." (PMID 35299889, 2022). "However, little was known about the correlation between PTBP1 and glioma and its prognostic significance in glioma patients." (PMID 35299889, 2022). "PTBP1 expression was statistically positively correlated with the estimated infiltration value of cancer-associated fibroblasts for TCGA tumors of SKCM, KIRP, and lower grade glioma, but negatively for testicular germ cell tumors." (PMID 36595978, 2022). "Furthermore, we used bioinformatics to predict the potential upstream mechanisms and downstream pathways of PTBP1's involvement in glioma progression." (PMID 35299889, 2022). "Moreover, we demonstrated that the expression of PTBP1 was positively correlated with glioma grading and poor prognosis, and PTBP1 promoted glioma cell proliferation, migration, and invasion by increasing the ratio of ITSN1-S/ITSN1-L." (PMID 36171198, 2022). "Finally, we found that TCF3 showed highly positive correlation with PTBP1 in glioma and was significantly higher in glioma compares to normal tissues (P < 0.001, r = 0.7)." (PMID 35299889, 2022). "Furthermore, we shed light on the underlying mechanism of PTBP1 by constructing a miR-218-TCF3-PTBP1 transcriptional network in glioma." (PMID 35299889, 2022). "Furthermore, in 693 glioma patient samples from CGGA, PTBP1 mRNA level was positively correlated with glioma grading." (PMID 36171198, 2022). "Finally, we summarized a proposed schema that PTBP1 enhanced the inclusion of ITSN1 exon 30 to promote glioma progression." (PMID 36171198, 2022). "PTBP1 gene is involved in the regulation of glioma, multiple myeloma, and hepatocellular carcinoma, but its role in pituitary adenoma is still unknown." (PMID 35836612, 2022). "Given the regulation of ITSN1 splicing by PTBP1, we then investigated whether PTBP1 induces glioma progression by modulating the ratio of ITSN1-S/ITSN1-L in the form of increasing ITSN1-S while decreasing ITSN1-L." (PMID 36171198, 2022). "Knockdown of MIR155HG by inhibiting the Wnt/β-catenin pathway via downregulation PTBP1 could increase glioma sensitivity to TMZ." (PMID 34178658, 2021). "The results indicated that PTBP1, circRNA_001160 and miR-195-5p could promote the transmembrane transport of Dox, thereby enhancing the role of Dox against glioma." (PMID 31862871, 2019). "In this study, we validated PTBP1, a putative biomarker for glioma, and tested the extent to which immunofluorescent microscopy combined with automated and unbiased image analysis would permit the utility of PTBP1 as a biomarker to distinguish diagnostically challenging surgical biopsies." (PMID 28282372, 2017). "Recent study has shown that the splicing switch of pyruvate kinase in human gliomas may be controlled by c-myc through splicing factors including polypyrimidine tract binding protein (PTBP1)." (PMID 21501490, 2011). "Interestingly, PTBP1 overexpression abolished the effect of circYIPF6 silencing on the proliferation (P < 0.01), apoptosis (P < 0.001), and glycolysis (P < 0.01) of glioma cells." (PMID 37588107, 2023). "Furthermore, PTBP1 expression in glioma was upregulated (P < 0.01)." (PMID 37588107, 2023). "PTBP1 may be a potential therapeutic target for glioma, particularly for GBM." (PMID 35299889, 2022). "In contrast, single-cell analysis based on the CancerSEA database revealed that PTBP1 and NCAPG are associated with various functions such as cell cycle, DNA damage, DNA repair, and proliferation, suggesting that they may be involved in the malignant progression of glioma." (PMID 41438761, 2025). "Knockdown of both PTBP1 and PTBP2 slowed glioma cell proliferation, and PTBP2 null mice died shortly after birth and exhibited misregulation of alternative splicing in genes involved in cytoskeletal remodeling and cell proliferation." (PMID 40113750, 2025).